CDK1 (cyclin dependent kinase 1)
Diseases named in the same sentence as CDK1 in open-access papers (continued):
Sharing a sentence is not in itself a finding about the gene and the disease.
ovarian carcinoma (continued). "Taken together, our results suggest that phosphorylation of MLK3 by CDK1 and CDK2 is important for the regulation of MLK3 and c-Jun N-terminal kinase activities during G1/S, G2, and M phases in ovarian cancer cell division." (PMID 35843311, 2022). "We observed that CDK1 inhibition with RO3306 or CGP74514A blocks MLK3 phosphorylation in M phase cells in both normal and ovarian cancer cells." (PMID 35843311, 2022). "We showed that CDK1 and CDK2 regulate MLK3 to control JNK activity during cell cycle progression in human ovarian cancer cells." (PMID 35843311, 2022). "The HPA database was used to verify histological levels of TTK, NEK2, and CDK1, and results suggested that TTK, NEK2, and CDK1 were upregulated in ovarian cancer tissue compared to the normal tissue." (PMID 34072728, 2021). "Many other genes in the cell cycle pathway, such as CDC7, CDK1 and CHEK1, have previously been reported to be correlated with the proliferation and chemoresistance of ovarian cancer." (PMID 34876569, 2021). "Targeting mitotic control, either by selective inhibition of CDK1 or aberrant activation of CDK1 via Wee1 inhibition, has been successful in increasing the efficacy of PTX in breast and ovarian cancers." (PMID 34370741, 2021). "The protein expression levels of CCNA2, CCNB1, CDC20, CDCA8, CDK1, KIF11 and TOP2A were high in ovarian cancer tissues, which was further confirmed via the HPA database." (PMID 34253236, 2021). "We demonstrated that circ-NOLC1 promotes ovarian cancer tumorigenesis and development by binding to ESRP1 and modulating CDK1 and RhoA levels." (PMID 33483472, 2021). "We have earlier reported NSC777201 for some biological activities, herein, we used a molecular docking approach and an NCI’s ovarian cancer cell lines to evaluate its anti-cancer activity and explore its possibility for targeting TTK, NEK2, and CDK1." (PMID 34072728, 2021). "The results of the HOUP hub genes confirmed that the expression levels of TNF, ESR1, CDK1, CXCR4 and MUC1, indicating these 5 hypomethylated genes were activated in ovarian cancer development." (PMID 32192517, 2020). "Using real-time PCR, we found that silencing SMYD3 significantly decreased the mRNA levels of CCNA2, CCNB2, CCND2, CDK1 and CDK2 (p<0.05) but increased the mRNA levels of WEE1 (p<0.05), suggesting an essential role for SMYD3 in ovarian carcinoma proliferation." (PMID 31417652, 2019). "The protein expressions of 5 hub genes (CDK1, TOP2A, CDC20, NCAPG, and MELK) are significantly up-regulated in ovarian cancer compared to normal tissues." (PMID 30453999, 2018). "The CDK1 activator, Response Gene to Complement-32 (RGC-32, C13ORF15), is overexpressed in colon, breast and ovarian cancer tissues and we have detected selective high-level RGC-32 protein expression in EBV-immortalized latency III cells." (PMID 22163048, 2011). "To further validate the relationship between ODF2L and the response to WEE1 inhibition in EOC, we examined the correlation of ODF2L levels, CDK1 activity, and cell viability in a panel of AZD1775-treated primary EOC cells derived from 57 tissue samples from patients with ovarian cancer." (PMID 36378528, 2023). "Unlike SKOV3, TOV112D, and HEY ovarian cancer cells, T80 and T29 normal ovarian epithelial cells did not exhibit decreased levels of p-CDK1, p-CDK2, or p-Rb when treated with URMC099." (PMID 35843311, 2022). "We propose a model in which CDK1 and CDK2 phosphorylate MLK3, and this phosphorylation works as a “on/off” switch that in turn regulates MLK3 and JNK activity to control cell cycle progression in ovarian cancer cells." (PMID 35843311, 2022).
ovarian carcinoma (continued). "Studies demonstrated that α-pinene inhibits cell growth in prostate cancer and ovarian cancer, and induces G2/M cell cycle arrest through up-regulation of Chk1 and Chk2 levels and down-regulation of cyclin B1, CDC25 and CDK1 levels in hepatoma carcinoma BEL-7402 cells." (PMID 34151367, 2021). "Furthermore, we used the GEPIA web-based tool to investigate the roles of these genes in ovarian cancer; interestingly, we found that expressions of TTK, NEK2, and CDK1 were correlated with tumor stages." (PMID 34072728, 2021). "An extensive literature search revealed that ESRP1 was also overexpressed in ovarian cancer tissues; therefore, we suggested that circ-NOLC1 could bind with ESRP1 and modulating CDK1 and RhoA expression." (PMID 33483472, 2021). "NSC777201 demonstrated antiproliferative and dose-dependent anticancer activity against the NCI’s ovarian cancer cell lines, and its further evaluation towards TTK, NEK2, and CDK1 inhibition was carried out with in silico docking in a receptor-ligand interaction study." (PMID 34072728, 2021). "Based on GO functional analysis, KEGG pathway analysis, and survival analysis, we found that CDK1, TOP2A, and UBE2C might be the core genes contributing to the development of epithelial ovarian cancer at the molecular level." (PMID 30453999, 2018). "We revealed that tissue microarray blocks of epithelial ovarian cancer (n = 249) showed increased level of cytoplasmic Cdk1 (p < 0.001), but not in nucleus (p = 0.192) of histologic cell type independently." (PMID 27385216, 2016). "Even there are large numbers of TMA slide cores which were stained cytoplasmic Cdk1 without nucleus Cdk1 staining in ovarian cancer." (PMID 27385216, 2016). "This investigation highlighted CCNA2, TRIP13, CDK1, CDC20 and PRC1 as viable targets for our structure-based drug discovery campaign, as they all had a crystallised structure available in the Protein Data Bank, strong evidence of a role in ovarian cancer and known inhibitors." (PMID 39184376, 2024). "Interestingly, by analyzing The Cancer Genome Atlas (TCGA) ovarian carcinoma (OV) database, we noticed that, similar to the strong correlation between the levels of WEE1 and PKMYT1 and that of their substrate CDK1, the level of ODF2L also significantly correlated with that of CDK1." (PMID 36378528, 2023). "Based on the results of the DTB of SKOV3 cells and the differences in JNK activity in late G1/S, early G2, and M phases, we hypothesized that CDK2 (during early G2 phase) and CDK1 (during early M phase) plays an essential role in regulating MLK3 and JNK activity in ovarian cancer cells." (PMID 35843311, 2022). "Thus, we hypothesized that circ-NOLC1 might participate in ovarian cancer tumorigenesis and progression by binding the ESRP1, thus modulating RhoA and CDK1 expression." (PMID 33483472, 2021). "Moreover, our meta-analysis identified three specific genes, namely, CDK1, TOP2A and UBE2C, which may be potential targets of ovarian cancer." (PMID 30453999, 2018). "Hence, we speculated that, aberrant activation of CDK1 might enhance the activity of MPF and promote ovarian cancer cells mitosis and proliferation persistently." (PMID 28899430, 2017). "There is whether cytoplasmic cdk1 which was elevated in the ovarian cancer can have activity, or not." (PMID 27385216, 2016). "Although the decrease in BRCA1 activity upon Cdk1 inhibition was not prominent for combined treatment of RO-3360 and Cisplatin, it is certain that the inhibition of Cdk1 was significantly suppressed cell growth and promoted apoptosis of ovarian cancer cell lines treated with cisplatin." (PMID 27385216, 2016).
ovarian carcinoma (continued). "Western blot analysis of the ovarian cancer cells shows an increase in apoptotic markers, such as cleaved PARP, cleaved caspase-3, Apaf-1, Bim, Bad, and Bid, in the si-Cdk1 transfected cells than in the si-negative control cells, in a time-dependent manner." (PMID 27385216, 2016). "Ovarian cancer cell lines (OVCA-429, OVCAR-3, SK-OV-3, and OVCA-433) were transfected with si-negative control and si-Cdk1 and were incubated for 72 h." (PMID 27385216, 2016). "Notably, our study is among the first to propose Naringin as a natural compound capable of simultaneously targeting CDK1 and WEE1, based on both docking affinity and dynamic binding stability—an aspect not explored in prior ovarian cancer studies." (PMID 41009727, 2025).
prostate carcinoma (87 papers, 2010 to 2026). A carcinoma that arises from epithelial cells of the prostate gland. "The malignant proliferation and migration of prostate cancer caused by ABCC5 was significantly eliminated by inhibiting CDK1 activity." (PMID 33994848, 2021). "The Cancer Genome Atlas (TCGA) database shows that elevated expression levels of cdk1 are associated with shorter disease-free survival of prostate cancer patients, and particularly of CRPC patients." (PMID 31010254, 2019). "We show that inhibition of OGT activity inhibits the proliferation of prostate cancer cells, leads to sustained loss of c-MYC and suppresses the expression of CDK1, elevated expression of which predicts prostate cancer recurrence (p=0.00179)." (PMID 26824323, 2016). "To further address this, we analyzed the accumulation of CDK1 in 109 carcinomas of the prostate (60 low grade, 49 high grade) and looked for its association with tumor grade." (PMID 25149538, 2014). "Association of CDK1 accumulation and tumor grade was statistically significant in this series of prostatic cancers (p<0.05, from Fisher's exact test)." (PMID 25149538, 2014). "In the data presented here, ganetespib exposure resulted in G2/M accumulation and loss of S phase in prostate cancer cells, mediated at least in part through loss of the checkpoint regulatory proteins CDK1 and CHK1." (PMID 23152004, 2013). "ABCC5 facilitates prostate cancer advancement and enzalutamide resistance through the CDK1-mediated AR Ser81 phosphorylation pathway." (PMID 41363115, 2025). "To find the effects of green tea extract on PC3 prostate cancer cells through inhibition of cell proliferation, we investigate the expression of cyclin B1 and CDK1 (that are important to mitosis progress) utilizing the western blot technique." (PMID 40336533, 2025). "DATS treatment decreased the levels of CDK1 and increased the levels of universal cell cycle inhibitor Cip1/p21 protein, as earlier reported in studies of prostate cancer and gastric cancer." (PMID 38254868, 2024). "Mechanically, TPX2 mediates prostate cancer EMT through cyclin-dependent kinase (CDK1)-regulated phosphorylation of ERK/GSK3β/SNAIL pathway." (PMID 36707511, 2023). "The paracancerous tissues exhibit lower expression of CDK1 compared to gastric cancer tissues, with high CDK1 expressing patients displaying lower survival rates, and CDK1 has been termed an independent prognostic factor for Prostate cancer." (PMID 36769170, 2023). "In support of this it was shown that the expression of CDK1 is required for an integrin-dependent stimulation of prostate cancer cell migration." (PMID 35626034, 2022). "Another study showed that protein phosphatase1alpha mobilization of CDK1 mediated by a positive feedback loop had been shown to drive androgen receptors in prostate cancer." (PMID 35330393, 2022). "Instead, E2F1/E2F2 hinder premature CDK1 activation during S phase, which is key to ensure genome stability and viability of prostate cancer cells." (PMID 36230876, 2022). "Mechanism studies have shown that matrine, one of the main ingredients of CKI, exhibits time-dependent inhibition of CDK1 expression in prostate cancer cells, resulting in o cell cycle arrest in the G0/G1 phase, thereby inhibiting cancer cell proliferation." (PMID 35236335, 2022). "In this study, we discovered the mechanism of ABCC5 in tumor development, namely, promoting malignant phenotypes such as proliferation and migration of prostate cancer by stabilizing CDK1 protein levels and activating ERK signaling pathways." (PMID 33994848, 2021). "Inhibition of CDK1 not only eliminates the cancer-promoting effect of ABCC5 in prostate cancer but also increases the sensitivity of prostate cancer cells to enzalutamide." (PMID 33994848, 2021). "First, this study did not determine which specific protein is the E3 ligase that mediates CDK1 ubiquitination in prostate cancer." (PMID 33994848, 2021).
prostate carcinoma (continued). "Previous studies have demonstrated that high expression of CDK1 facilitates the poor prognosis of prostate cancer 45-48." (PMID 33994848, 2021). "CDK1 expression was mainly involved in prostate cancer, small cell lung cancer, and GC and was enriched in the WNT signaling pathway and T cell receptor signaling pathway." (PMID 33365314, 2020). "In prostate cancer, it affected expression of protein B1, cyclin-dependent kinase 1 (CDK1), and other related molecules in the G2/M cell cycle of PC-3 and 22RV1 cells." (PMID 32256642, 2020). "VPA administration has been shown to counteract temsirolimus resistance in prostate cancer cells by reducing cdk1/cyclin B and the mTORC1 member Raptor." (PMID 31010254, 2019). "Accordingly, next-generation sequencing of CRPC signatures has revealed that cdk1 significantly predicts survival of patients with prostate cancer." (PMID 31010254, 2019). "Analysis of a published prostate cancer microarray data set revealed that increased expression of CDK1 predicts prostate cancer recurrence after surgery with high significance (p = 0.00179)." (PMID 26824323, 2016). "So far, we have established an inhibitor dose that displayed a clear decrease in the expression of an important cell cycle regulator, CDK1, and a decrease in the expression of AR, a major drug target in prostate cancer." (PMID 26824323, 2016). "Recently, the cdk1/2-cyclin A/B complex has been identified as critically involved in resistance development of prostate cancer cells." (PMID 25444514, 2015). "miR-31 has a known role in prostate cancer and melanoma, suppressing key cell cycle regulators and pro-oncogenic genes such as CDK1, E2F2, EXO1, FOXM1, MCM2, Src or MET." (PMID 25644061, 2015). "As expected, prostate cancer PPC1 cells subjected to Cdk1 knockdown showed G2-M phase arrest; however, Cdk1 knockdown did not sensitize PPC1 cells to Fas or TRAIL (data not shown)." (PMID 25790448, 2015). "VPA diminished cdk1 in all prostate cancer cell lines, whereas cdk2 and cdk4 were reduced in DU-145 and LNCaP, but not in PC-3 cells." (PMID 21867506, 2011). "Notably, it was shown that CDK1 was expressed at relatively higher levels in prostate cancer tissues than in normal tissues." (PMID 40336533, 2025). "Indeed, high expressions of CDC20, PLK1 and CDK1 correlate with prostate cancer occurrence and worse biochemical recurrence survival rates." (PMID 37509260, 2023). "In addition, it has been reported that the activation of CDK1/SPOP signaling by the ATR inhibition enhanced the cytotoxicity of ICIs in prostate cancer." (PMID 37528490, 2023). "After topological enrichment, the most connected upregulated genes MYC, CDK1, CCNB1 etc. and the most connected downregulated genes EGFR, VEGFA, STAT3 etc. were categorized according to their highest degree count associated with prostate cancer." (PMID 35456461, 2022). "To verify whether CDK1 mediates the pro-oncogenic effect of ABCC5 in prostate cancer, we knocked down CDK1 again in prostate cancer cells overexpressing ABCC5 and performed a series of tumor phenotyping experiments." (PMID 33994848, 2021). "ISL induces cell apoptosis in prostate cancer cells through G2/M cell cycle arrest with concomitant downregulation of cyclin B1, CDK1 (p-Thr14, p-Tyr15, and p-Thr161) (after 48 h of treatment, the IC50 of ISL on PC-3 and 22RV1 is 19.6 and 36.6 μM, respectively)." (PMID 33401375, 2021). "To fully test our hypothesis, we examined the protein expression levels of ABCC5 and CDK1 in our own prostate cancer cohort and revealed that the protein expression of CDK1 was highly positively correlated with the protein expression of ABCC5." (PMID 33994848, 2021). "Moreover, the addition of a CDK1 inhibitor or knockdown of CDK1 significantly improved the efficacy of enzalutamide on prostate cancer cells." (PMID 33994848, 2021).